LGALS1 (galectin 1)
Diseases named in the same sentence as LGALS1 in open-access papers (continued):
Sharing a sentence is not in itself a finding about the gene and the disease.
diabetes (continued). "In addition, we carried out antibody-based blockade of Il-1β and Tlr4 to validate the association of these macrophage-related molecules with diabetes-induced Lgals1 expression in the mouse retina." (PMID 29170525, 2017). "Experimental data suggest that galectin-1 may modulate kidney fibrosis in mouse models of diabetes." (PMID 34743218, 2022). "The metabolic role of galectin-1 in tissues other than the adipose tissue could also provide novel insights into the role of galectin-1 in the development of T2D, as well as in the context of the development of diabetes-related complications." (PMID 36295832, 2022). "Furthermore, galectin-1 and diabetes were correlated in this study and in previous reports." (PMID 31996694, 2020). "Glucocorticoid treatment to mice significantly alleviated diabetes‐induced retinal HIF‐1α and galectin‐1/Lgals1 levels, while increasing TSC22D3 expression." (PMID 32150332, 2020). "To further confirm the in vitro suppressive effect of glucocorticoids on IL‐1β‐induced galectin‐1/LGALS1 expression, we used the in vivo model of STZ‐induced diabetes in mice." (PMID 31328390, 2019). "Compared with nondiabetic patients, patients with diabetes had higher levels of serum galectin-1, more proteinuria, lower hemoglobin and total cholesterol levels, and reduced LVEFs." (PMID 31996694, 2020). "Therefore, diabetes-induced retinal AGE accumulation was suggested to activate IL-1β-related inflammatory cues in macrophages followed by Müller cells, linking to galectin-1 upregulation in human DR with time." (PMID 29170525, 2017). "Furthermore, the expression of the fibrosis marker fibronectin increased in murine proximal tubular cells cultured in high glucose conditions but was ameliorated when treated with the galectin-1 inhibitor OTX008, indicating a role of galectin-1 in diabetes induced fibrosis." (PMID 36295832, 2022). "The inhibition of galectin-1 by OTX008 in DR may preserve retinal pigment epithelial cell integrity and functionality by reducing their pro-fibrotic phenotype and epithelial–mesenchymal transition phenomenon induced by diabetes." (PMID 35897964, 2022). "We also sought to clarify whether the possible predictive role of galectin-1 would be independent of diabetes." (PMID 31996694, 2020). "In this study, we investigated protein levels of galectin-1 in eyes with the different clinical stages of DR, and explored upstream regulatory stimuli for hypoxia-unrelated galectin-1 expression selectively in the pathogenesis of DR but not non-diabetic retinal vascular occlusions." (PMID 29170525, 2017). "In summary, diabetes-induced generation and accumulation of AGE were suggested to activate IL-1β-related inflammatory cues in monocyte-derived macrophages/microglia followed by Müller glia, linking to the upregulation of galectin-1 along with the severity of DR." (PMID 29170525, 2017). "In this single-center observational study, the serum galectin-1 concentration was associated with eGFR decline during a mean follow-up period of 1.4 ± 1.1 years in 798 patients with stable angina undergoing elective CAG, irrespective of the presence of diabetes." (PMID 31996694, 2020). "Here we reveal a significant upregulation of galectin-1 in eyes of DR patients along with progression of clinical stages beginning from the pre-ischemic, inflammatory stage with diabetic macular edema, but not in eyes with non-diabetic retinal vascular occlusions." (PMID 29170525, 2017). "Although not a predictor of CIN, the circulating serum galectin-1 level is an independent prognostic marker for subsequent renal function decline in patients undergoing CAG, irrespective of diabetes." (PMID 31996694, 2020).
colorectal cancer (20 papers, 2014 to 2026). A primary or metastatic malignant neoplasm that affects the colon or rectum. "Another important signature, LGALS1, is known to undergo significant changes during colorectal cancer development and metastasis, and it has been implicated in various normal and pathological processes." (PMID 38580967, 2024). "The gene LGALS1, encoding galectin-1, is usually hypermethylated in colorectal cancer cells—its induction by demethylating treatments induces apoptosis because of down-regulation of Wnt signaling." (PMID 28481247, 2017). "Metylation inactivation of LGALS1 was associated with angiogenesis in colorectal cancer, but silencing this gene may be responsible for angiogenesis in EOC." (PMID 30970615, 2019). "In colorectal cancer, tRF-3022b, an exosomal tRF, binds to galectin-1 (LGALS1) and macrophage migration inhibitory factor (MIF), modulating MIF levels to reduce M2 macrophage polarization, which impacts tumor growth." (PMID 41376858, 2026). "SK induces apoptosis and autophagy of colorectal cancer cells by targeting galectin-1 and JNK signaling pathways in vitro and in vivo." (PMID 35293266, 2022). "In colorectal cancer SW-620 cells, shikonin promoted galectin-1 dimerization and triggered apoptosis in a ROS-dependent manner." (PMID 34829701, 2021). "Shikonin promoted galectin-1 dimer, then activated Jun N-terminal protein kinase (JNK), and eventually caused apoptosis and autophagy in colorectal cancer." (PMID 34829701, 2021). "Previous studies have shown that LYAR promotes the migration and invasion of colorectal cancer cells by activating the expression of galectin-1." (PMID 34696677, 2021). "For example, a study investigating circulating galectins as colorectal cancer markers found that galectin-1 was significantly increased in patients with colorectal cancer compared with healthy controls." (PMID 34638303, 2021). "The activation of Galectin-1 induced by shikonin potently activated apoptosis in colorectal carcinoma cells and autophagic cell death both in vitro and in vivo." (PMID 31892852, 2020). "In order to further determine the role of galectins, especially galectin-1 in shikonin-induced colorectal carcinoma cells apoptosis, we overexpressed galectin-1 in SW620 and HCT116 cells and found the two cell lines became more sensitive to shikonin." (PMID 31892852, 2020). "We plan to measure the serum levels of galectin-1, galectin-3, and 90K/Mac-2BP of patients at different stages of colorectal cancer and analyze the correlation of these galectins with stages of colorectal cancers." (PMID 26448934, 2015). "Although little is known about the transcriptional regulation of galectin-1 in colorectal cancer (CRC), it has been clearly shown that galectin-1 plays an important role in the regulation of cell migration in colon cancer." (PMID 26413750, 2015). "Four galectins, galectin-1, galectin-3, galectin-4, and galectin-8, are expressed in the human colon and rectum and their expressions show significant changes during colorectal cancer development and metastasis." (PMID 26448934, 2015). "Galectin-1 was significantly altered during the development of various malignant tumors and metastases, including colorectal cancer." (PMID 26413750, 2015). "Higher galectin-1 concentration was correlated with lymph node metastasis, especially in colorectal cancer patients with normal CEA." (PMID 26448934, 2015). "tRF-3022b, which may affect colorectal cancer tumor growth and polarization of M2 macrophages by binding LGALS1 and MIF." (PMID 40726981, 2025). "In colorectal cancer patients even with normal carcinoembryonic antigen, serum galectin-1 could predict more lymph node metastasis." (PMID 26448934, 2015). "Galectin-1 could predict more lymph node metastasis in colorectal cancer patients with normal serum carcinoembryonic antigen." (PMID 26448934, 2015).
colorectal cancer (continued). "Furthermore, we downregulated the level of galectin-1 in colorectal carcinoma cells by siRNA and evaluated whether this process would influence cell apoptosis." (PMID 31892852, 2020). "tRF-3022b binds to the effects of lectin 1 (LGALS1) and macrophage migration inhibitor (MIF) in colorectal cancer cells, and by regulating MIF in M2 macrophages." (PMID 40726981, 2025). "We confidently identified known prognostic biomarkers for colorectal cancer, such as S100A4, LGALS1, and FABP5." (PMID 38580967, 2024). "In colorectal cancer patients, galectin-1 attenuated cytotoxic CD8+ T-cell-killing activity and showed high expression, especially in stroma cells, which led to poor overall survival in colorectal cancer patients." (PMID 37371482, 2023). "In addition, the heterogeneity of solid tumors makes it unlikely that upregulating the expression of LGALS1 is the only molecular mechanism by which LYAR promotes CRC migration and invasion among all colorectal cancers with high LYAR expression." (PMID 35069968, 2021). "Even in the same kind of tumor, the role of different galectins is not also the same; for example, galectin-1 is overexpressed and can increase metastasis of colorectal cancer while Gal-4 is downregulated in colorectal cancer." (PMID 29854732, 2018). "In colorectal cancer, galectin-1 expression is silenced by promoter hypermethylation, resulting in reduced apoptosis, while in mixed lineage leukemia (MLL)-rearranged B-lymphoblastic leukemias, galectin-1 is overexpressed, because of the histone methylation of the LGALS1 promoter." (PMID 25256425, 2014).
Insulin resistance (20 papers, 2021 to 2026). Increased resistance towards insulin, that is, diminished effectiveness of insulin in reducing blood glucose levels. "Epidemiological studies have reported an association between galectin-1 and insulin resistance variables." (PMID 38469554, 2024). "Galectin-1 levels were negatively associated with glucose and positively associated with C-peptide levels, fasting insulin, and insulin resistance measured as HOMA and the Matsuda index." (PMID 38777863, 2024). "We also showed that galectin-1 was associated with the insulin resistance marker TyG-index in the group with radiographic hand OA." (PMID 38469554, 2024). "Studies in humans have been demonstrating an association between galectin-1 and lifestyle, genetics as well as insulin resistance in recent years, underlining a potential role of galectin-1 in these processes." (PMID 36295832, 2022). "Galectin-1 has anti-inflammatory properties and has also been associated with several inflammatory markers increased in human insulin resistance, including IL-6, TNF-α and CRP." (PMID 36295832, 2022). "Large population-based cohorts have demonstrated associations for circulating galectin-1 and markers of insulin resistance and incident type 2 diabetes." (PMID 36295832, 2022). "Here, genetically elevated galectin-1 was associated with higher eGFR (p = 5.7 × 10−3) specifically in individuals with severely insulin-resistant T2D, a group previously known to have an elevated risk of diabetic nephropathy." (PMID 36295832, 2022). "However, in similarity with galectin-1, it was associated with TyG index, a marker of insulin resistance that is superior to HOMA-index in Nonalcoholic Fatty Liver Disease (NAFLD)." (PMID 38777863, 2024). "The different associations for plasma galectin-1 and -3 with the various markers of insulin resistance may reflect involvement in different metabolic contexts, which should be validated in mechanistic studies." (PMID 38777863, 2024). "The strong cross-sectional association of galectin-1 with BMI, insulin resistance and markers of renal function could suggest a joint role for galectin-1 in these processes." (PMID 34743218, 2022). "We found its positive association with BMI, glycated hemoglobin, leptin, insulin, IL-8 and IL-10 levels supporting a galectin-1 interconnection with glucose control, insulin resistance and inflammation." (PMID 40698658, 2025). "While the largest body of evidence for a role of galectin-1 in insulin resistance is currently focused on the adipose tissue, galectin-1 is altered in many different cells in the insulin resistant state." (PMID 36295832, 2022). "One of the first to indicate a role for galectin-1 in insulin resistance was a study of 10 obese but otherwise healthy insulin-resistant men treated with the insulin sensitizing PPAR-γ agonist rosiglitazone (4 mg bid) for 14 days." (PMID 36295832, 2022). "As a role for galectin-1 in insulin resistance becomes more apparent, the distinct role of galectin-1 in the pathophysiological mechanisms in this state appear complex." (PMID 36295832, 2022). "The scientific evidence for a possible role of galectin-1 as a mediator of pathophysiological mechanisms behind insulin resistance has also increased in recent years, as several clinical studies have presented similar results in this area." (PMID 36295832, 2022). "The reduced inflammation observed in the adipose tissues of Lgals1−/− mice suggested that galectin-1 targeting improved insulin resistance." (PMID 33431823, 2021). "Several animal models also demonstrate a role of galectin-1 in insulin resistance." (PMID 36295832, 2022). "Our results indicate that galectin-1 levels may not directly affect type 2 diabetes risk but do not exclude a mediating role affecting insulin resistance, e.g. through lifestyle." (PMID 34743218, 2022).
Insulin resistance (continued). "Differences in study design may explain the large variety in different signalling pathways proposed for galectin-1 in insulin resistance and highlight the need for additional mechanistic studies elucidating which of these interactions are of highest clinical relevance." (PMID 36295832, 2022). "This study did not observe any difference in circulating levels of galectin-1 between the groups but did report positive correlations between serum galectin-1 and the insulin resistance related variables fat cell size and waist-hip ratio." (PMID 36295832, 2022).
ovarian carcinoma (20 papers, 2005 to 2025). A malignant neoplasm originating from the surface ovarian epithelium. "The Galectin-1 levels were found to be associated with various variables of Ovarian Cancer patients." (PMID 34556165, 2021). "In contrast, elevated mRNA level of LGALS1 was significantly associated with a poor OS in total patients with ovarian cancer, with HR=1.35(1.16-1.56), P < 0.001." (PMID 33854625, 2021). "In this report, we showed that galectin-1 was able to be released from ovarian cancer cells and cancer associated fibroblasts." (PMID 26589590, 2015). "galectin-1 has been implicated in tumor invasion and metastasis and is frequently over-expressed in epithelial ovarian cancer (EOC), but its potential as a biomarker remains unclear." (PMID 26589590, 2015). "Studies on ovarian cancer have shown that the downregulation of Galectin-1 with siRNA-based strategies increases the mRNA levels of E-cadherin and decreases the levels of N-cadherin, MMP7, fibronectin, Snail, and Slug, thereby inhibiting the EMT pathway." (PMID 39996781, 2025). "Galectin-1 overexpression promotes cisplatin resistance in ovarian cancer cells and doxorubicin resistance in triple-negative breast cancer cells, indicating the association of Galectin-1 signal transduction with cancer drug resistance." (PMID 37433225, 2023). "Galectin-1 is likely to enhance the proliferation and invasiveness of ovarian cancer cells, and its expression level is positively correlated with tumour stage and lower susceptibility to chemotherapy with cisplatin." (PMID 37238197, 2023). "On the other hand, in ovarian cancer cells, galectin-1 released in response to TLR4 induced EMT through the phosphatidylinositol 3-kinase (PI3K)/AKT pathway." (PMID 34356834, 2021). "Consistently, we found that high level of LGALS1 was significantly related to a poor OS in total patients with ovarian cancer, especially with serous, stages III+IV and grade II cancer." (PMID 33854625, 2021). "Conversely, LGALS1 protein expression in ovarian cancer tissues (8.45±0.63) was significantly higher than that in normal ovarian samples (2.02± 1.05) (P<0.001)." (PMID 33854625, 2021). "In ovarian cancer cells, forced galectin-1 overexpression induced EMT through the MAPK JNK/p38 pathway." (PMID 34356834, 2021). "It has been found that Galectin-1 (Gal-1) is an indicator of poor prognosis in ovarian cancer patients where high expression of Gal-1 is observed in ovarian cancers of higher histological grade as well as advanced lymph node status." (PMID 34174910, 2021). "In surprise, LGALS1 mRNA expression in normal ovarian cell was significantly lower than that in ovarian cancer ES2 and A2780 cell lines, but significantly higher than that in ovarian cancer OVCAR-3 cell line (P < 0.05)." (PMID 33854625, 2021). "Galectin-1 has been detected in various malignancies like pancreatic cancer, hepatocellular cancer, prostate cancer, ovarian cancer and breast cancer." (PMID 34556165, 2021). "a) Ovarian tumour type: Galectin-1 levels in serum of patients with malignant ovarian tumours (45.35±19.88 ng/ml) were found to be higher significantly as compared to the controls (9.1±4.6 ng/ml) and benign ovarian tumours (10.0 ±5.29 ng/ml) (p<0.0001)." (PMID 34556165, 2021). "In ovarian cancer, however, most previous studies focused on galectin-1, -3 and -7 as prognostic factors." (PMID 29361803, 2018). "Galectin-1 overexpression has been indicated to promote progression and chemoresistance towards cisplatin in epithelial ovarian cancer." (PMID 26859293, 2016). "Galectin-1 is known to be a hypoxia regulated protein, and has been suggested as inducing the progression of chemoresistance in epithelial ovarian cancer." (PMID 26859293, 2016). "Emerging research has demonstrated that galectin-1 overexpression can lead to chemoresistance towards cisplatin in epithelial ovarian cancer." (PMID 26859293, 2016).
ovarian carcinoma (continued). "The levels of galectin-1 expression in CAS cells of epithelial ovarian cancer tissues varied among patients." (PMID 26589590, 2015). "Recently, it has been shown that galectin-1 is strongly expressed in ovarian cancer and promotes progression and chemoresistance to cisplatin in epithelial ovarian cancer." (PMID 26589590, 2015). "The study emphasizes that serum Galectin-1 may serve as a better surrogate biomarker in Ovarian Cancer for early detection, discriminating between malignant and benign abdominal masses and monitoring the progression of the disease and response to treatment." (PMID 34556165, 2021). "Moreover, galectin-1 accumulation in the peritumoral stroma of breast cancer and ovarian cancer regulates both cancer cell proliferation and invasiveness." (PMID 26589590, 2015). "galectin-1 has emerged as a protein commonly elevated in ovarian cancer." (PMID 26589590, 2015). "After showing the increased expression of galectin-1 in epithelial ovarian cancerous tissue compared to the normal ovarian tissue by western blot and qRT-PCR analysis, we investigated the level of galectin-1 expression in the pathologic specimen of EOC patients using the IHC method." (PMID 26589590, 2015). "LGALS1, LGALS3, LGALS4, LGALS8 and LGALS9 were found to be overexpressed in ovarian cancer patients." (PMID 37238197, 2023). "In total patients with ovarian cancer, LGALS4, LGALS8, LGALS10 and LGALS13 mRNA levels were related to a better OS, and LGALS1 to a worse OS." (PMID 33854625, 2021). "In head and neck SQ20B and A2780-1A9 ovarian cancer cell lines, PTX008 treatment resulted in a decreased level of Galectin-1 expression at 48 and 72 h and reduced phospho-Erk starting as soon as 2 h post-treatment." (PMID 29580262, 2018). "Galectin-1 and galectin-3 are both up-regulated in among others bladder carcinoma, head and neck squamous cell carcinoma (HNSCC) and ovarian cancer." (PMID 24658839, 2014). "Increased expression of galectin-1 in primary ovarian cancer tissue has been demonstrated, while it is absent in normal tissue." (PMID 37238197, 2023). "LGALS1 predicted a worse OS in women with serous, stages III+IV or grade II ovarian cancer." (PMID 33854625, 2021). "The protein level of LGALS1, LGALS4, LGALS8, LGALS10 and LGALS13 in ovarian cancer cell lines were all decreased compared with those in the normal ovarian cell (all P<0.05)." (PMID 33854625, 2021).